DRP2 (dystrophin related protein 2)
Description:
Required for normal myelination and for normal organization of the cytoplasm and the formation of Cajal bands in myelinating Schwann cells. Required for normal PRX location at appositions between the abaxonal surface of the myelin sheath and the Schwann cell plasma membrane. Possibly involved in membrane-cytoskeleton interactions of the central nervous system.
Synonyms: DRP-2
Tractability: Antibody: UniProt places it where antibodies can reach, with medium confidence; its Gene Ontology location is reachable by antibodies, with medium confidence; the Human Protein Atlas places it where antibodies can reach.
Gene: Protein-coding gene on chromosome X (101,219,769 to 101,264,502, forward strand). Ensembl gene ENSG00000102385.
Subcellular location: Postsynaptic density; Cell projection, dendrite; Perikaryon; Cell membrane
Subcellular location (Human Protein Atlas): Nuclear speckles; Plasma membrane
Pathways (Reactome):
Developmental Biology: EGR2 and SOX10-mediated initiation of Schwann cell myelination
Extracellular matrix organization: Formation of the dystrophin-glycoprotein complex (DGC)
Gene Ontology:
Molecular function: zinc ion binding
Biological process: central nervous system development; synaptic signaling; synapse organization
Cellular component: perikaryon; plasma membrane; postsynaptic density; dendrite; glutamatergic synapse
Homologues: Orthologues: chimpanzee DRP2 (99% identical), rabbit DRP2 (96% identical), dog DRP2 (96% identical), guinea pig DRP2 (96% identical), rat Drp2 (96% identical), macaque DRP2 (96% identical), pig DRP2 (95% identical), mouse Drp2 (95% identical), tropical clawed frog drp2 (69% identical), zebrafish drp2 (65% identical). Paralogues in human: DMD (53% identical), UTRN (50% identical), MACF1 (17% identical), DST (15% identical), PLEC (13% identical), SYNE1 (12% identical), SPTBN5 (12% identical), SPTB (11% identical), SPTAN1 (11% identical), MICAL3 (11% identical), SPTBN4 (11% identical), DSP (11% identical), and 24 more.
Diseases named in the same sentence as DRP2 in open-access papers:
DRP2 is named in the same sentence as 25 diseases in open-access papers, as found by Europe PMC text mining. Sharing a sentence is not in itself a finding about the gene and the disease. The quoted sentences say what the papers report.
Alzheimer disease (4 papers, 2011 to 2024). A progressive, neurodegenerative disease characterized by loss of function and death of nerve cells in several areas of the brain leading to loss of cognitive function such as memory and language. "One of the clinical diagnostic features of Alzheimer’s disease is a loss of memory, consistent with a loss of DRP2 function and its reduced levels." (PMID 38790679, 2024). "In addition, elevated GSK-3β activity is also associated with Alzheimer’s disease and there is a direct link with hyperphosphorylation of DRP2 at GSK-3β-dependent phosphorylation sites and increased amyloid precursor protein." (PMID 37175950, 2023).
Cerebral ischemia (3 papers, 2020 to 2023). Restriction of arterial blood supply to the brain associated with insufficient oxygenation to support the metabolic requirements of the tissue. "The new knowledge reported here identifies DRP2 as a new target to promote neuronal survival after cerebral ischemia." (PMID 37175950, 2023). "Further analysis and research of DRP2 as a key protein in the neuroprotection mechanism in cerebral ischemia could constitute a possible target for therapeutic action." (PMID 37175950, 2023). "Interestingly, our results showed DRP2 markedly upregulated in reperfusion after cerebral ischemia on DRP2 isoforms with more acidic pI values, indicative of hyperphosphorylation states, reducing the potential neuronal repair in response to ischemic injury." (PMID 37175950, 2023). "Moreover, there are other studies that found an increase in DRP2 after brain ischemia in rats." (PMID 37175950, 2023). "This DRP2 phosphorylation regulation has been a target for therapeutic intervention, with treatments that regulate the Akt–GSK-3β–DRP2 signalling pathway in cerebral ischemia." (PMID 37175950, 2023). "Furthermore, proteins as HSC70, DRP2, enolase 1, UCHL1, ADK1, and particularly NDKA and even more Rho-GDI, exhibit higher association levels to 4E-BP2 in cerebral cortex and could be considered as biomarkers of resilience to cerebral ischemia." (PMID 34638676, 2021).
ischemia (3 papers, 2020 to 2023). A hypoperfusion of the BLOOD through an organ or tissue caused by a PATHOLOGIC CONSTRICTION or obstruction of its BLOOD VESSELS, or an absence of BLOOD CIRCULATION. "Therefore, we can conclude an association between DRP2–4E-BP2–eIF4E in the vulnerable CA1 region after ischemia reperfusion that would reduce the availability of “active” eIF4E (unbound to 4E-BP2), essential to protein synthesis, an association that would be dependent on DRP2 phosphorylation." (PMID 37175950, 2023). "After these results, DRP2 has emerged as a potential biomarker for ischemia, although the role of its different isoforms in the molecular mechanism of ischemic pathology must be elucidated." (PMID 34638676, 2021). "These treatments prevented the decrease of phospho-Akt and phospho-GSK-3β levels induced by ischemia, reducing the ischemia-induced increase of phospho-DRP2 by “active” dephospho-GSK-3β, and improving the integrity and protection of axons/dendrites against ischemic injury." (PMID 37175950, 2023). "DRP2 has been described in diverse global and focal ischemia models, identifying different phosphorylated forms, or isoforms of DRP2 with different response to ischemia." (PMID 34638676, 2021). "The differential DRP2 isoforms in brain tissue reported here are certainly findings that require further studies in order to confirm the DRP2-phosphorylation-dependent mechanism involved in the regulation of 4E-BP2 and eIF4E in ischemia reperfusion." (PMID 37175950, 2023). "On the contrary, carbonylation level of dihydropyrimidinase related protein 2 (DRP-2) and l-lactate dehydrogenase B chain (LDHB) were slightly increased in CA1 but remarkably increased in DG after ischemia." (PMID 33041514, 2020). "It is considered that DRP-2 and LDHB are specific targets of oxidative stress by ischemia insult and high carbonylation levels of DRP-2 may play an important role in modulating ischemic neuronal death." (PMID 33041514, 2020).
cerebral infarct (2 papers, 2021 to 2023). "DRP2 was found in human cerebral infarct samples from stroke patients, detecting DRP2 isoforms by 2D DIGE with different pI values and being downregulated or upregulated depending on the DRP2 isoform." (PMID 37175950, 2023).
schizophrenia (2 papers, 2015 to 2019). A major psychotic disorder characterized by abnormalities in the perception or expression of reality. "The other high expression level gene in breast tumors was DRP2, which is associated with paranoid-type schizophrenia." (PMID 31182966, 2019).
brain cancer (1 paper, 2019). A primary or metastatic malignant neoplasm affecting the brain. "Some study suggests a relationship between DRP2 and lung cancer and brain cancer." (PMID 31182966, 2019).
breast carcinoma (1 paper, 2019). "Finally, 6 upregulated DEGs (CST2, DRP2, CLEC5A, SCD, KIAA1211, DTL) and 6 downregulated DEGs (STAC2, BTNL9, CA4, CD300LG, GPIHBP1 and PIGR), were confirmed in a quantitative real time PCR comparison of breast cancer and paracancerous breast tissues from 8 clinical specimens." (PMID 31182966, 2019).
glioma (1 paper, 2021). A benign or malignant brain and spinal cord tumor that arises from glial cells (astrocytes, oligodendrocytes, ependymal cells). "This does not mean that DRP2, IGFBP5, KLF10, ARHGAP11A and NRP2 are not essential genes for glioma pathogenesis, given the missing data and limited sample size we found." (PMID 34434651, 2021). "Among them, ARHGAP11A, DRP2, HNRNPA3, KLF10, PAIP1, and RCN1 have not yet been studied in gliomas." (PMID 34434651, 2021).
Intellectual disability (1 paper, 2016). "Several genes related to intellectual disability (Dcaf17, Myst4, Park2, Rbfox1) were found to be hypo-methylated in male pups, and genes (Pfn1, Cntnap1, Drp2) related to normal function of the nervous system were hypo-methylated in female pups from the HMFA group." (PMID 27199632, 2016).
muscular dystrophy (1 paper, 2024). Muscular dystrophy (MD) refers to a group of more than 30 genetic diseases characterized by progressive weakness and degeneration of the skeletal muscles that control movement. "Among these, pig DRP2 emerged as an anti-muscular dystrophy-associated protein in rats, effectively inhibiting muscular dystrophy and exhibiting a close association with normal skeletal muscle development in humans." (PMID 39457877, 2024).
neuropathy (1 paper, 2019). A disorder affecting the nervous system that manifests with pain, tingling, numbness, and/or muscle weakness. "Although the association of Periaxin mutations was confirmed in autosomal recessive CMT4F neuropathy, DRP2 null mice showed weak myelin abnormality." (PMID 31217940, 2019). "Herein, we report a mutation in DRP2 gene in a family with neuropathy and provide the evidence of DRP2 contribution in CMT-like symptoms." (PMID 31217940, 2019). "Here, by means of WES strategy, we found a novel mutation in dystrophin related protein 2 (DRP2) gene in two brothers of a family with symptom of neuropathy similar to CMT." (PMID 31217940, 2019).
polyneuropathy (1 paper, 2019). A disease or disorder affecting more than one nerve. "Here, we presented a novel variant on DRP2 genes in two brothers of a family with symptom of polyneuropathy." (PMID 31217940, 2019).
Stroke (1 paper, 2023). Sudden impairment of blood flow to a part of the brain due to occlusion or rupture of an artery to the brain. "Moreover, DRP2 has been detected, with increased or decreased levels, in postmortem brain samples and cerebral microdialysis from stroke patients." (PMID 37175950, 2023). "Recently, it has been reported that Toll-like receptor four (TLR4) promotes the phosphorylation of DRP2 via activation of Rho-kinase two in MCAO rats, suggesting that this mechanism may mediate the pathological outcome of TLR4 in stroke." (PMID 37175950, 2023).
transient cerebral ischemia (1 paper, 2023). "Here, using a proteomic approach in a model of transient cerebral ischemia, a detailed study of DRP2 was performed in order to address the challenge of translation restoration in vulnerable regions." (PMID 37175950, 2023).
cancer (1 paper, 2022). A tumor composed of atypical neoplastic, often pleomorphic cells that invade other tissues. "DRP2 is a crucial molecule in extracellular matrix-receptor interaction pathways and has been reported to be related to cancer development." (PMID 35222524, 2022).
neurodegenerative disease (1 paper, 2011). A disorder of the central nervous system characterized by gradual and progressive loss of neural tissue and neurologic function. "In our study, we present five proteins that are also regulated in neurodegenerative diseases: UCHL-1, transhtyretin, Apolipoprotein A1, DRP-2 and DRP-3." (PMID 21470419, 2011).
peripheral neuropathy (1 paper, 2020). A disorder affecting the peripheral nervous system. "Indeed, Prx-/- mice display a progressive peripheral neuropathy including axon/myelin-units with abnormal myelin thickness, demyelination, tomaculae, onion bulbs, reduced nerve conduction velocity, reduced abundance and mislocalization of the periaxin-associated DRP2 and reduced internode length." (PMID 32130108, 2020).
DRP2 also shares sentences with these, for which no sentence is quoted: autism (1 paper); autism spectrum disorder (1); brain tumor (1); breast tumors (1); hypertrophic cardiomyopathy (1); lung carcinoma (1); Parkinson disease (1); X-linked agammaglobulinemia (1).